ZNF211 (zinc finger protein 211)
Description:
May be involved in transcriptional regulation.
Synonyms: ZNF-25; CH2H2-25; C2H2-25
Tractability: PROTAC: ubiquitination databases record sites on it.
Gene: Protein-coding gene on chromosome 19 (57,630,395 to 57,644,044, forward strand). Ensembl gene ENSG00000121417.
Subcellular location: Nucleus
Subcellular location (Human Protein Atlas): Mitochondria; Rods & Rings
Pathways (Reactome):
Gene expression (Transcription): Generic Transcription Pathway
Gene Ontology:
Molecular function: DNA-binding transcription factor activity, RNA polymerase II-specific; RNA polymerase II cis-regulatory region sequence-specific DNA binding
Biological process: regulation of transcription by RNA polymerase II; negative regulation of DNA-templated transcription; regulation of DNA-templated transcription
Cellular component: nucleus
Genetic constraint (gnomAD): Loss-of-function variants: 18 observed, 12.07 expected, observed/expected ratio (o/e) 1.49, 90% interval 1.01 to 1.92. The upper end of that interval is the gene's LOEUF score, 1.92, which puts it in group 6 of 6, group 1 being the genes least tolerant of losing a copy. Missense variants: 677 observed, 721.36 expected, observed/expected ratio (o/e) 0.94, 90% interval 0.88 to 1. Synonymous variants: 249 observed, 251.55 expected, observed/expected ratio (o/e) 0.99, 90% interval 0.89 to 1.1.
Homologues: Orthologues: chimpanzee ZNF211 (99% identical), Caenorhabditis elegans ztf-16 (13% identical), zebrafish prdm2a (12% identical), Caenorhabditis elegans sdz-12 (10% identical), Caenorhabditis elegans ehn-3 (10% identical), Drosophila melanogaster CG12769 (7% identical). Paralogues in human: ZNF445 (36% identical), ZNF786 (36% identical), ZNF597 (21% identical), ZNF423 (19% identical), ZNF521 (19% identical), ZNF462 (18% identical), ZBTB39 (14% identical).
Diseases named in the same sentence as ZNF211 in open-access papers:
ZNF211 is named in the same sentence as 2 diseases in open-access papers, as found by Europe PMC text mining. Sharing a sentence is not in itself a finding about the gene and the disease. The quoted sentences say what the papers report.
tumor (1 paper, 2015). "Twenty candidate genes (84%) showed methylation in greater than 50% of primary tumor, including ADFP, FUZ, ZNF71, ENPP5, ZNF211, and ZNF14." (PMID 26544568, 2015).
ZNF211 also shares sentences with these, for which no sentence is quoted: cancer (2 papers).